CDKN2A (cyclin dependent kinase inhibitor 2A)
Diseases named in the same sentence as CDKN2A in open-access papers (continued):
Sharing a sentence is not in itself a finding about the gene and the disease.
mesothelioma (continued). "Additionally, deletion of CDKN2A is not useful in distinguishing mesothelioma from metastatic lung tumors, a common clinical problem in mesothelioma diagnosis." (PMID 30060501, 2018). "Moreover, there was a greater reduction in tumor volume observed in patients with MTAP-negative mesotheliomas compared to those with MTAP-positive mesotheliomas, suggesting that CDKN2A and MTAP codeletions may select for patients who will derive a greater benefit from abemaciclib." (PMID 38610930, 2024).
leukemia (96 papers, 2007 to 2025). A malignant (clonal) hematologic disorder, involving hematopoietic stem cells and characterized by the presence of primitive or atypical myeloid or lymphoid cells in the bone marrow and the blood. "Prior research has already established noteworthy connections between CDKN2A polymorphisms and susceptibility to this childhood leukemia, however, substantial associations are still awaiting validation." (PMID 39443269, 2024). "Leukemia development was observed at a low penetrance when combined with the loss of one of the alleles of Kdm5c/Pax5/Cdkn2a or when exposed to infections." (PMID 37670323, 2023). "The introduction of targeted pax5 and cdkn2a/b gene mutations, mimicking secondary mutations, in the E::R line significantly increased the incidence in leukemia." (PMID 38136366, 2023). "Together, these findings demonstrate that mutational activation of IL7RA cooperates with CDKN2A silencing in progression to leukemia." (PMID 35115489, 2022). "Twelve Sca1‐Lmo2 leukemias were analyzed and revealed copy number loss of Cdkn2a/b (2/12) and Bcl11b (4/12), similar to human T‐ALL, as well as c‐Myc amplification (8/12)." (PMID 29880602, 2018). "BCR-ABL+ (i.e., Ph+) leukemia has a poor prognosis; this is particularly true when matched with deletions in Cdkn2a, the gene encoding the tumor suppressor protein ARF, which occurs frequently in B-ALL." (PMID 28683103, 2017). "Pol2 stalling and convT strongly associate with recurrent breakpoint sites across the genome and at gene loci implicated in leukemia such as CDKN2A and PAX5." (PMID 27431763, 2016). "Treatment alternatives for cases of leukemia with CDKN2A mutations encompass the targeting of the CDK2-SKP2 axis, the utilization of the small-molecule CDK4/6 inhibitor known as palbociclib, and the application of the innovative CDK2/9 inhibitor referred to as fadraciclib." (PMID 39443269, 2024). "CDKN2A genetic variation is associated with leukemia incidence and prognosis." (PMID 36275721, 2022). "In addition, the meta-analysis indicated that hypermethylation of CDKN2A gene was associated with the increased risk of leukemia (P = 0.006, OR = 3.53, 95% CI = 1.43–8.73)." (PMID 24810788, 2014). "Previous research identified loss of heterozygosity (LOH) on chromosome 9p and biallelic deletions of CDKN2A as critical factors for aggressive disease in childhood leukemia." (PMID 40805197, 2025). "Secondary mutations in other genes (paired box 5/PAX5, cyclin-dependent kinase inhibitor 2A/CDKN2A, etc.)are postulated to be requisite for the full development of leukemia, and together they accelerate the onset and progression of leukemia." (PMID 40584293, 2025). "Given the prior association between CDKN2A/2B promoter silencing with malignant transformation, we sought to compare the methylation status of the locus in CMV-specific T cells versus leukemia." (PMID 38867059, 2024). "In vivo ATRA treatment in secondary recipients of Cdkn2a-WT MYB::PLEKHO1 or Cdkn2a-KO MYB::PLEKHO1 leukemias resulted in a significant reduction in disease burden." (PMID 39499902, 2024). "Cdkn2a-WT MYB::PLEKHO1 leukemias showed intact expression of p16INK4A and p19ARF, while Cdkn2a-KO leukemias did not, confirming that MYB::PLEKHO1 is indeed able to induce leukemia independently of Cdkn2a loss." (PMID 39499902, 2024). "The fusion partner evidently plays a role in the leukemogenicity of the MYB fusion, since MYB::PLEKHO1 can induce leukemia independently while MYB-TR requires KO of Cdkn2a." (PMID 39499902, 2024). "We first treated Cdkn2a-KO MYB::PLEKHO1 leukemia cells harvested from mouse spleens with ATRA in vitro." (PMID 39499902, 2024). "Two Early-Pro cases, Ph28-D and Ph50-D, harbored concurrent deletions of EBF1, PAX5, RUNX1 and CDKN2A/B and clustered between Early-Pro and Late-Pro leukemias in PCA." (PMID 37337105, 2023). "Our results show that leukemia incidence is significantly increased by secondary lesions in the pax5 and cdkn2a/b genes." (PMID 38136366, 2023).
leukemia (continued). "Late-Pro leukemias were also significantly enriched for homozygous deletions of CDKN2A/B and RB1 (P = 0.0013 and 0.0047)." (PMID 37337105, 2023). "The co-existence of PAX5, CDKN2A, and IKZF1 mutations classifies this leukemia as “Ikaros plus” high-risk ALL30." (PMID 35115489, 2022). "As a secondary genetic event in the development of leukemia, the CDKN2A/B deletions were found in approximately 20%–25% of B-cell precursor acute lymphoblastic leukemia (BCP-ALL) and 38.5%–50% of T-ALL patients." (PMID 35712467, 2022). "Other alterations that are common in T-ALL, such as MYB amplification, LEF1 deletion, and CDKN2A/B deletions, are also rare in both types of immature leukemia." (PMID 35626077, 2022). "We further demonstrated the critical role of CDKN2A in IL7RA-activated B-cell progenitors for the progression to full-blown leukemia." (PMID 35115489, 2022). "The editing of CDKN2A in addition to the IL7RAins mutant was also confirmed by exome sequencing of the three leukemias." (PMID 35115489, 2022). "We investigated the effects of THS exposure in utero and during early life in a transgenic Cdkn2a knockout mouse model that is vulnerable to the development of leukemia/lymphoma." (PMID 33851706, 2021). "We investigated the effects of in utero and early-life THS exposure on plasma cytokines, body weight, hematologic parameters and leukemia/lymphoma development using the Cdkn2a null mouse model of childhood ALL." (PMID 33851706, 2021). "We describe here that, indeed, MOZ-TIF2 silences expression of the CDKN2A locus (p16INK4a and p19ARF), inhibits the triggering of senescence and enhances proliferation, providing conditions favorable to the development of leukemia." (PMID 26854485, 2016). "Evidence shows that there are characteristics exclusive to specific leukemias, including deletion of BTG1 in B-cell leukemia, loss of IKZF1 with monosomy 7 in AML, and deletions involving IGH, TCR, IKZF1, and CDKN2A/B in CML-AP/CP." (PMID 27233483, 2016). "According to the results of our meta-analysis, the aberrant DNA methylation at CDKN2A gene and CDKN2B gene were risk factors for leukemia, especially for AML." (PMID 24810788, 2014). "A further subgroup meta-analysis by subtype of leukemia showed that CDKN2A, CDKN2B, ID4 genes were significantly hypermethylated in acute myeloid leukemia." (PMID 24810788, 2014). "Many deletions (i.e., Cdkn2a, Ebf1, Pax5, Ikzf1) involved B-cell development genes and tumor suppressor genes, recapitulating deletions occurring in human leukemia." (PMID 23487523, 2012). "Recent evidence suggests that translocations act in concert with other genetic lesions to induce overt leukemia including deletion of genes such as cyclin-dependent kinase inhibitor 2A gene (CDKN2A) or the more recently described deletion of IKZF1 (Ikaros)." (PMID 21386967, 2011). "With the progress of gene research in the field of leukemia and the further expansion of sample size, CDKN2A/B deletion may be included as a criterion for intermediate risk in the stratification of pediatric ALL patients." (PMID 40017529, 2025). "A higher incidence of leukemia occurred after introducing additional genetic defects through methods such as chemical mutagenesis, Sleeping Beauty transposon expression, or crossbreeding with mice harboring Pax5 or Cdkn2a/b deletions." (PMID 38136366, 2023). "This strongly suggests that Hhex’s well-documented function in HSCs and leukaemia via PRC2-mediated repression of Cdkn2a may also be one of its primary roles in the adult pancreas." (PMID 37398663, 2023).
leukemia (continued). "In ALL Cdkn2a is a tumor suppressor involved in cell cycle regulation, and in our disease model there was an acute response to the disease during the early stages of leukemia development, but this response was attenuated as the disease progressed." (PMID 33154494, 2020). "Single-cell multicolour FISH was used to demonstrate that the earliest detectable leukaemia subclone contained the STIL-TAL1 fusion and copy number loss of 9p21.3 (CDKN2A/CDKN2B locus), with other copy number alterations including loss of PTEN occurring as secondary subclonal events." (PMID 29556024, 2018). "We also observed a lower frequency of alterations affecting CDKN2A than has been found in childhood leukaemia, suggesting that its role in iT‐ALL leukaemogenesis may be less important than in childhood T‐ALL or B lineage ALL." (PMID 26205622, 2015). "Indeed, when additional mutations were separately introduced into the zebrafish orthologs of the human PAX5 and CDKN2A/B genes, which are deleted in a quarter of the E::R leukemias, the incidence increased to 15% and 7%, respectively, which is similar to what has been observed in mice." (PMID 38136366, 2023). "Amongst the re-expressed genes were CDKN2A, EIF2AK2, TNFSF10 and XAFI, all of which are associated with cell cycle inhibition or induction of cell death through increasing caspase activity and the reduction of which are known to be associated with the development of leukemia." (PMID 28881658, 2017). "Hoxb8-FL cell–derived leukemia was almost fully penetrant in Cdkn2a-WT MYB::PLEKHO1, Cdkn2a-KO MYB-TR, and Cdkn2a-KO MYB::PLEKHO1 recipient mice but was rarely observed in other genotypes and only with significantly longer latency." (PMID 39499902, 2024). "Compared with normal B cells, high expression of cell proliferation markers such as Mki67, Cdk6, Cdkn2a and Hist1h1b, was noted in this cluster, indicating a BBC2 leukemia cell identity." (PMID 38730491, 2024). "Since FVB/N mice that lack Cdkn2a are cancer-prone, primarily developing leukemia/lymphoma and sarcoma, we transplanted BM of THS-exposed and control Cdkn2a null mice into histocompatible BM-ablated recipient animals." (PMID 33851706, 2021). "The authors postulate that deletions of the following genes ETV6, VPREB1, CDKN2A/B, TBL1XR1, PAX5 as well as BTLA and CD200 are very early and essential events in leukemia development." (PMID 27933341, 2016). "To investigate why MYB::PLEKHO1 but not MYB-TR initiated leukemia in Cdkn2a-WT Hoxb8-FL cells, we developed a system to culture MYB-expressing Hoxb8-FL cells in vitro without requiring Hoxb8 activation." (PMID 39499902, 2024). "In contrast to MYB-TR, MYB::PLEKHO1 did not require Cdkn2a KO to initiate leukemia in Hoxb8-FL cells." (PMID 39499902, 2024). "Our study of E::R;pax5mut and E::R;cdkn2a/b leukemias lacks control data without the E::R fusion gene." (PMID 38136366, 2023). "Similar to what occurs in BCP-ALL, T-ALL also shows a specific association of CDKN2A/B deletions with a particular subgroup of patients, specifically with the non-immature T-ALL leukemias." (PMID 33435487, 2021). "This suggests that MYB-TR activates the G1/S cell cycle checkpoint and could explain why MYB-TR Hoxb8-FL.MS5 cells have a slow growth rate in vitro, and MYB-TR is unable to induce leukemia in vivo without KO of Cdkn2a." (PMID 39499902, 2024).
leukemia (continued). "Importantly, expression of the most frequently mutated genes in T cell lymphoma or leukemia (i.e., DNMT3A, TET2, JAK, NOTCH1, CDKN2A, PTEN, and FBXW7) was not altered in miR-H18-BCMA CAR T cells." (PMID 35821635, 2022). "In the present study, we utilized the Cdkn2a null mouse model of childhood ALL to address in utero and early-life THS exposure effects, from the first day of pregnancy through weaning, on plasma cytokines, body weight, hematologic parameters and leukemia/lymphoma development." (PMID 33851706, 2021). "Interestingly, the gene that encodes ARF, CDKN2A, is frequently deleted in lymphoid, but not myeloid, BCR-ABL1-driven leukaemia." (PMID 25753524, 2015). "However, CDKN2A/B deletions do not occur in CML; probably because the leukemia arises from HSC-like progenitors, in which the CDKN2A/B locus is epigenetically silenced and “poised” to respond to an abnormally higher and sustained threshold of hyperproliferative signals." (PMID 33435487, 2021).
sarcoma (95 papers, 2010 to 2025). A usually aggressive malignant neoplasm of the soft tissue or bone. "Deregulation of the CDKN2A-CCND-CDK4/6-retinoblastoma 1 (Rb) pathway is frequently observed in about 25% of unselected sarcomas and is a distinct pathogenic characteristic for specific subtypes." (PMID 38434982, 2024). "CDKN2A deletions and inactivating mutations seem to have a negative prognostic role across different tumor types, including sarcomas." (PMID 36741019, 2023). "Alteration of the CDKN2A gene was the only finding associated with worse OS across all sarcoma subtypes in a series of 7,733 sarcoma cases analyzed with next-generation sequencing (Foundation Medicine)." (PMID 37875500, 2023). "Our study identified a recently described as a new candidate sarcoma susceptibility gene, namely CDKN2A, which is worthy of further study." (PMID 36805510, 2023). "Given the widespread presence of CDK4‐amplification/high expression and CDKN2A loss across sarcomas subtypes, CDK4 inhibitors such as palbociclib are also a promising strategy in RB‐positive tumors." (PMID 33047515, 2020). "There is emerging data on germline CDKN2A mutations that predispose towards the development of sarcoma, however, we found that these cases were exceedingly rare (0.2%)." (PMID 31528332, 2019). "Genetic cooperation between RAS pathway activation and loss of Cdkn2a tumour suppressor function has been shown in other mouse models of sarcomas." (PMID 29731980, 2018). "Conversely, however, sarcomas are rare in CDKN2A mutation carriers, and the affected family of our cohort also does not present with sarcoma cases." (PMID 30086788, 2018). "CDKN2A mutations have been frequently detected in other UV-induced tumors as well as in few sarcomas." (PMID 26943575, 2016). "We previously reported rapid sarcoma induction by intramuscular implantation of Kras (G12V)-expressing, Cdkn2a (p16p19) deficient mouse myofiber-associated (MFA) cells into the extremity muscles of NOD." (PMID 26499495, 2015). "In 25% of DNA samples from sarcomas with qPCR values indicating Cdkn2a loss, exon 2 copy numbers were <0.2, which suggested the presence of a homozygous deletion in ∼80% of tumor cells, compatible with an early event in tumorigenesis." (PMID 21533183, 2011). "This study also found that many TFCP2 fusion sarcomas have CDKN2A loss." (PMID 40361368, 2025). "Remarkably, UPS are also among the most represented sarcoma histotypes with CDKN2A loss." (PMID 36741019, 2023). "By comparison, in certain sarcomas such as OS and EwS, CDKN2A loss is observed later in tumor genesis, suggesting that CDK activation in those tumors may promote progression rather than initiation." (PMID 32344731, 2020). "Dysregulation of the CDKN2A locus, due to either mutation or methylation, which encodes p16 and p19, has been reported in several subtypes of human sarcomas; consequently we examined if abrogation of this tumor suppressor in the RCAS-TVA system would promote sarcoma formation." (PMID 24733554, 2014). "Further investigation of the identified CpG site in the gene body of CDKN2A in combination with genetic alterations for a large cohort of these sarcoma subtypes may identify a new diagnostic option for stratification of high-grade pleomorphic sarcomas." (PMID 24345474, 2013). "The efficacy of PRMT5 inhibitors in the context of MTAP passenger deletions has been demonstrated in several cancers, suggesting that patients with FUS/EWSR1-TFCP2 sarcoma and CDKN2A/MTAP loss may also benefit from PRMT5 inhibitors, which are currently being tested in clinical trials." (PMID 38168093, 2024).